HSD17B6 (hydroxysteroid 17-beta dehydrogenase 6)
Diseases named in the same sentence as HSD17B6 in open-access papers:
HSD17B6 is named in the same sentence as 30 diseases in open-access papers, as found by Europe PMC text mining. Sharing a sentence is not in itself a finding about the gene and the disease. The quoted sentences say what the papers report.
hepatocellular carcinoma (7 papers, 2020 to 2024). A malignant tumor that arises from hepatocytes. "Promoter DNA methylation is a vital epigenetic mechanism to inhibit gene expression, and our previous study showed that it is the major contributor in regulating HSD17B6 expression in hepatocellular carcinoma." (PMID 34750355, 2021). "HSD17B6 has important functionality in androgen catabolism and was remarkably downregulated in hepatocellular carcinoma, which predicted poor prognosis and high tumor immune infiltrates." (PMID 34195087, 2021). "Similarly, hypermethylation of the HSD17B6 promoter was shown to decrease its expression, contributing to the progression of hepatocellular carcinoma." (PMID 38504159, 2024). "Reduced HSD17B6 expression correlates with tumor stage and grade in hepatocellular carcinoma." (PMID 37240140, 2023). "And we have reported that HSD17B6 expression was significantly lower in hepatocellular carcinoma." (PMID 34750355, 2021). "Previously, we showed that HSD17B6 inhibits malignant progression of hepatocellular carcinoma." (PMID 34750355, 2021). "However, little is known about the detailed role of HSD17B6 in hepatocellular carcinoma (HCC)." (PMID 32514254, 2020).
liver cancer (5 papers, 2020 to 2025). An epithelial or non-epithelial malignant neoplasm that arises from the liver. "For instance, HSD17B6 prevents liver cancer cell growth, migration, and invasion by regulating the expression of TGFB1." (PMID 38725005, 2024). "Accordingly, we found that HSD17B6 expression in liver cancer was significantly negatively correlated with multiple immune cell infiltration, such as dendritic cells, CD4+ T cells, and B cells." (PMID 32514254, 2020). "And treatment with 5-aza, an inhibitor of DNA methylation, upregulated the HSD17B6 mRNA and protein expression of liver cancer cells." (PMID 32514254, 2020). "HSD17B6 has been ascertained to be down-regulated in liver cancer and NSCLC." (PMID 39695810, 2024). "Moreover, the effects of HSD17B6 on the migrated and invasive abilities of liver cancer cells were assessed by wound‐healing assay and transwell assay respectively." (PMID 32514254, 2020). "Regarding HSD17B6, the OS and PFS increased with its expression in liver cancer, while for prostate cancer, it resulted in a worse prognosis." (PMID 36674737, 2023). "Especially, in Wurmbach Liver and Chen Liver dataset, although HSD17B6 was downregulated in HCC versus normal liver tissue, its expression level in liver cancer precursors was not significantly reduced." (PMID 32514254, 2020).
lung carcinoma (4 papers, 2015 to 2024). "Previous studies have suggested a role for dihydrotestosterone in modulating progress of various malignancies, and HSD17B6 dysfunction was associated with lung cancer and prostate cancer." (PMID 32514254, 2020). "Downregulated HSD17B6 has also been identified to be associated with non-small-cell lung cancer, implying that it might be the key gene contributing to tumorigenesis or tumor progression in lung cancer." (PMID 32514254, 2020). "Here, we found that HSD17B6 was negatively correlated with lung cancer tumor purity and positively correlated with CD8+ T cells." (PMID 38725005, 2024). "The disruption of METTL14 contributed to CD8+T-cell activation and the immunotherapy response to PD-1 via m6A modification of HSD17B6, thereby suppressing lung cancer progression." (PMID 38725005, 2024). "HSD17B6 was negatively correlated with lung cancer tumor purity and positively correlated with CD8+ T cells." (PMID 38725005, 2024). "Analysis of seven oncomine lung cancer datasets also showed that HSD17B6 mRNA levels were significantly reduced in LUAD compared with adjacent/healthy lung tissues." (PMID 34750355, 2021). "And shorter RFS was also observed in patients with LUAD expressing low levels of HSD17B6 in lung cancer datasets of oncomine and GEO datasets (p < 0.001 for “Okayama Lung”, p = 0.006 for GSE50081, p < 0.001 for GSE68465, respectively)." (PMID 34750355, 2021). "In addition, BSP analysis of CpG island upstream of HSD17B6 in lung cancer cell lines (H1299 and H1975) also showed its hypomethylation status." (PMID 34750355, 2021). "In addition, treatment with DHT, a syntenic product of HSD17B6, did not change the protein level of PTEN and p-Akt in these lung cancer cells, suggesting a DHT-independent function for HSD17B6 in LUAD tumorigenesis." (PMID 34750355, 2021).
lung adenocarcinoma (3 papers, 2021 to 2024). A carcinoma that arises from the lung and is characterized by the presence of malignant glandular epithelial cells. "In addition, HSD17B6 suppressed lung adenocarcinoma progression by activating the Akt signaling pathway." (PMID 38725005, 2024). "The analysis revealed that HSD17B6 expression was substantially lower in 11 kinds of tumors compared to the non-tumor tissues, including LUAD (Lung Adenocarcinoma), LUSC (Lung Squamous Cell Carcinoma), and so on." (PMID 34750355, 2021).
polycystic ovarian syndrome (3 papers, 2019 to 2023). "Previous studies have shown that polymorphisms of HSD17B6 gene are associated with polycystic ovary syndrome (PCOS)." (PMID 32514254, 2020). "Polymorphisms in the HSD17B6 gene are associated with polycystic ovary syndrome (PCOS) and key clinical phenotypes of the disorder." (PMID 32514254, 2020). "HSD17B6, hydroxysteroid 17-beta dehydrogenase 6, is involved in androgen catabolism and has been implicated in polycystic ovarian syndrome (PCOS), including metabolic perturbations correlated with PCOS, including increased BMI, fasting insulin, and insulin resistance." (PMID 37345113, 2023). "The intrinsic origin of ovarian steroidogenesis was increased due to the expression of HSD17B6 in theca cells of follicles in polycystic ovaries." (PMID 30944702, 2019).
prostate carcinoma (3 papers, 2015 to 2023). A carcinoma that arises from epithelial cells of the prostate gland. "Expression of HSD17B6 in prostate cancer samples with bone metastasis were significantly lower than that in non-metastatic counterparts, indicating the dysfunction of HSD17B6 in cancer metastases." (PMID 32514254, 2020). "The expression of HSD17B6 was significantly reduced in prostate cancer and it was undetectable in prostate cancers of Gleason grade higher than three." (PMID 32514254, 2020). "It has been reported that treatment with DHT, a product of HSD17B6, inhibited the expression of TGFB1 in prostate cancer." (PMID 32514254, 2020). "Its mRNA levels in castration resistant prostate cancer with bone metastatic samples were significantly lower than those without metastasis, indicating that HSD17B6 dysfunction involved in prostate cancer metastases." (PMID 32514254, 2020).
Hepatic fibrosis (2 papers, 2020 to 2025). The presence of excessive fibrous connective tissue in the liver. "Moreover, SNP of HSD17B6 was significantly associated with liver fibrosis risk." (PMID 32514254, 2020). "However, the deletion of Hsd17b6 does not affect fatty liver disease in terms of fat accumulation, inflammation, and hepatic fibrosis." (PMID 39896111, 2025).
Insulin resistance (2 papers, 2016 to 2023). Increased resistance towards insulin, that is, diminished effectiveness of insulin in reducing blood glucose levels. "The Hsd17b6 is suggested to act as a modifier gene influencing insulin resistance and obesity, and obese subjects show lower Hsd17b6 gene expression in the liver, whereas its gene expression is increased in the livers of obesity-resistant animals." (PMID 27213439, 2016).
Breast invasive carcinoma (1 paper, 2020). "Higher expression of HSD17B6 was only observed in BRCA (Breast invasive carcinoma) and HNSC (Head and Neck squamous cell carcinoma) compared to the normal." (PMID 32514254, 2020).
Cirrhosis (1 paper, 2020). A chronic disorder of the liver in which liver tissue becomes scarred and is partially replaced by regenerative nodules and fibrotic tissue resulting in loss of liver function. "Actually, cirrhotic patients with HCC had significantly lower plasma concentrations of several kinds of androgen including DHT, which was produced by HSD17B6, than patients with cirrhosis alone." (PMID 32514254, 2020).
diabetes (1 paper, 2022). "Our proteomic analysis and PRM validation confirmed that HSD17B2 and HSD17B6 were both significantly downregulated in db/db mice compared with bks mice, which could provide insights into the association between HSD17B2 or HSD17B6 and NAFLD and diabetes based on steroid metabolism." (PMID 36077090, 2022).
fatty liver disease (1 paper, 2025). A reversible condition wherein large vacuoles of triglyceride fat accumulate in liver cells via the process of steatosis. "•The hepatic expression of Hsd17b6 is associated with fatty liver disease." (PMID 39896111, 2025). "The expression of Hsd17b6 is correlated with diet-induced fatty liver disease, indicating it might play a role in the progression of MAFLD." (PMID 39896111, 2025). "•Hepatic Hsd17b6 is dispensable for diet-induced fatty liver disease." (PMID 39896111, 2025). "However, whether the manipulation of HSD17B6 could ameliorate diet-induced fatty liver disease remains unknown." (PMID 39896111, 2025). "Furthermore, the hepatic expression of Hsd17b6 is correlated with fatty liver disease." (PMID 39896111, 2025). "Taken together, our study suggests that the expression of Hsd17b6 is enriched in the liver and correlated with fatty liver disease but its hepatic deletion does not affect diet-induced fatty liver disease." (PMID 39896111, 2025).
liver disease (1 paper, 2020). "To investigate what alterations in HCC relate to HSD17B6, we analyzed the association between HSD17B6 mRNA expression levels and the clinical characteristics of HCC patients in TCGA and four liver disease microarray datasets from the Oncomine Platform." (PMID 32514254, 2020).
ovarian endometrioid stromal sarcoma (1 paper, 2016). "Diseases associated with HSD17B6 include ovarian endometrioid stromal sarcoma and ovary sarcoma." (PMID 27906043, 2016).
ovarian tumours (1 paper, 2023). "In addition, increased expression of the E1 synthetic enzymes HSD17B2, HSD17B4 and HSD17B6 in ovarian tumours is inversely associated with the probability of PPS (HR = 1.21 (1–1.45), p = 0.045; HR = 1.29 (1.07–1.55), p = 0.0073; respectively)." (PMID 36674737, 2023). "Moreover, elevated intratumoural E1 synthesis by HSD17B2, HSD17B4, HSD17B6 and HSD17B14 overexpression in primary ovarian tumours correlate with lower OS." (PMID 36674737, 2023).
prostate tumor (1 paper, 2013). "A similar shift from primarily HSD17B6 expression in non-malignant and primary prostate tumor tissue to mainly HSD17B10 expression in PC metastases was furthermore noted." (PMID 24244276, 2013).
tumor (11 papers, 2015 to 2024). "The abnormal expression of HSD17B6 is closely associated with the progression of multiple tumors and can be used to assess the level of immune cell infiltration in tumor tissues." (PMID 38725005, 2024). "HSD17B6 was down-expressed in LUAD, and the expression level of HSD17B6 was negatively associated with tumor stage." (PMID 33996569, 2021). "In accordance with this, lower expression of HSD17B6 was associated with larger tumor size in Wurmbach liver dataset." (PMID 32514254, 2020). "Therefore, loss of HSD17B6 functions in LUAD conferred tumor cell resistance against radiotherapy, thus leading to poor prognosis in patients." (PMID 34750355, 2021). "Lower expression of HSD17B6 was associated with worse T stage (data from TCGA, data from Liao Liver dataset), which refers to the size and extent of the main tumor." (PMID 32514254, 2020). "Furthermore, we showed here that loss of HSD17B6 affected the androgen biosynthesis and androgen signaling pathway, promoted tumor cell proliferation, migration, invasion, immune cell infiltration and immune evasion partially through TGFB1." (PMID 32514254, 2020). "What’s more, TGF-β promoted infiltration of immune cells and cancer-associated fibroblasts in the tumor microenvironments, and our present study showed that HSD17B6 could inhibit the expression of TGFB1." (PMID 32514254, 2020). "HSD17B6 inhibited tumor cell proliferation, EMT, invasion, and radioresistance through inhibiting AKT and its downstream signaling pathways." (PMID 34750355, 2021). "In summary, low HSD17B6 is frequently observed in LUAD and is associated with advanced tumor stage, grade, and poor prognosis in LUAD, resulting from high miR-31-5p expression in LUAD." (PMID 34750355, 2021). "In this study, using bioinformatics analyses of public datasets and experimentation, we have illustrated the key tumor suppressive roles of HSD17B6 in HCC samples." (PMID 32514254, 2020). "HSD17B6 expression was significantly lower in most of tumor tissues, including LIHC (Liver hepatocellular carcinoma), compared to the normal tissues (p < 0.001)." (PMID 32514254, 2020). "HSD17B6 exhibited a strong association with tumor-infiltrating B cells, CD4+ and CD8+ T cells, neutrophils, dendritic cells, and macrophages.It has been proposed by earlier research that HSD17B6 may prevent tumor growth." (PMID 38725005, 2024). "In the present study, the tumor suppressor role of HSD17B6 in LUAD was clarified." (PMID 34750355, 2021). "The protein encoded by HSD17B6 could convert 3-α-Adiol to DHT, dysregulation of which influence the progression of multiple kinds of tumor." (PMID 34750355, 2021). "Moreover, the tumor weight at the end of the experiment was also markedly lower in the HSD17B6-overexpressing group than in control group." (PMID 34750355, 2021). "Our findings indicate that HSD17B6 may function as a tumor suppressor in LUAD and could be a promising prognostic indicator for LUAD patients, especially for those receiving radiotherapy." (PMID 34750355, 2021). "The correlations between HSD17B6 and tumor immune infiltrates was investigated via TIMER and xCell." (PMID 32514254, 2020). "HCC with low expression of HSD17B6 has worse tumor stage and prognosis." (PMID 32514254, 2020). "In addition, protein levels of HSD17B6 were significantly lower in LUAD than adjacent para-cancerous tissues by analyzing CPTAC (Clinical Proteomic Tumor Analysis Consortium) LUAD dataset (p < 0.0001), which was in accordance with the analysis of mRNA expression." (PMID 34750355, 2021). "Previous studies suggested that HSD17B6 might inhibit tumor progression." (PMID 34750355, 2021). "Taken together, our outcome demonstrated the influence of GATA1/HSD17B6 regulatory axis in cisplatin resistance in LUAD, adding weight to the importance of therapeutic targets to enhancing tumor chemotherapy sensitivity." (PMID 39695810, 2024). "However, the mechanisms underlying inhibiting tumor development by HSD17B6 are not clear." (PMID 34750355, 2021).
tumor (continued). "First, we showed here that low expression of HSD17B6 led to high expression of TGFB1 through DHT, and then promoted tumor development in HCC." (PMID 32514254, 2020). "HSD17B6 expression was lower in HCC compared to normal liver and correlated with tumor stage and grade." (PMID 32514254, 2020). "HSD17B6 expression is lower in HCC than in normal liver tissue, and it can inhibit the proliferation, migration, and invasion of HCC cells, and is related to tumor grading and staging." (PMID 37589009, 2023). "In addition, HSD17B6 overexpression suppressed the expression of MMP2 and MMP9, which are critical proteinases for tumor invasion and metastasis through degrading extracellular matrix and vascular basement membrane." (PMID 34750355, 2021). "HSD17B6 may inhibit the expression of TGFB1 or other genes, and then inhibit tumor cell proliferation and invasion, immune cell infiltration and immune evasion." (PMID 32514254, 2020). "Moreover, HSD17B6, could be a novel biomarker for the biological behavior of HCC, serving as a putative tumor suppressor gene." (PMID 32514254, 2020).
cancer (3 papers, 2020 to 2023). A tumor composed of atypical neoplastic, often pleomorphic cells that invade other tissues. "Impressively, TK1, RRM2 and IMPDH1 were positively correlated with Myc/Myc signatures in multiple cancer types, whereas HSD17B6, PYGM and ACACB were negatively correlated with Myc/Myc signatures." (PMID 36629054, 2023). "It is also unclear how HSD17B6 regulates invasion and metastasis in cancer cells." (PMID 34750355, 2021). "In addition, treatment with 5-aza-2′-deoxycytidine, a DNA-hypomethylating agent, upregulated the mRNA expression of HSD17B6 in live cancer cell lines (HepG2, Hep3B and HuH-7) based on the data from GSE5230 and GSE35313 datasets (p < 0.05)." (PMID 32514254, 2020). "Our study is the first to analyze the differential expression of HSD17B6 in HCC tissues using different public datasets and examine its roles in cancer-related signaling pathways to identify its likely biological significance in HCC carcinogenesis." (PMID 32514254, 2020). "However, the detailed mechanism by which HSD17B6 influences cancer progression in LUAD was not investigated." (PMID 34750355, 2021).
HSD17B6 also shares sentences with these, for which no sentence is quoted: ovarian carcinoma (2 papers); breast carcinoma (1); head and neck squamous cell carcinoma (1); hypospadias (1); Lung Squamous Cell Carcinoma (1); metastasis (1); non-small cell lung carcinoma (1); Obesity (1); ovary sarcoma (1); schizophrenia (1); Simpson-Golabi-Behmel syndrome (1); staphylococcus aureus infection (1).